B2M (beta-2-microglobulin)
Diseases named in the same sentence as B2M in open-access papers (continued):
Sharing a sentence is not in itself a finding about the gene and the disease.
Sepsis (8 papers, 2019 to 2025). Sepsis is defined as life-threatening organ dysfunction caused by a dysregulated host response to infection. "B2M is a circulating factor positively associated with the sepsis patients and indicative of a suspected sepsis‐induced kidney injury." (PMID 34825737, 2022). "Yet, complete B2M deletion shortens pig lifespan, with affected animals developing fever around four weeks of age and succumbing to septicemia, as evidenced by multiorgan lymph node enlargement and bacterial infiltrates observed during autopsy." (PMID 41050672, 2025). "New diagnostic biomarkers of sepsis were screened by iTRAQ2D‐LC MS/MS, and proteins of ApoC3, VCAM1, B2M, and ApoE provide a supplement to classical biomarkers for septic diagnosis." (PMID 34825737, 2022). "The levels of VCAM1 (p = 0.010), B2M (p = 0.004), and ApoE (p = 0.039) were showing an increased tread in three groups, with the peak values of B2M and ApoE in the sepsis group." (PMID 34825737, 2022). "The levels of VCAM1 (p = 0.010), B2M (p = 0.004), and ApoE (p = 0.039) were showing an increased tread in three groups, and B2M and ApoE were showing peak values in the sepsis group." (PMID 34825737, 2022). "In our study, serum B2M level was showing an increased tread among non‐sepsis, sepsis, and septic shock groups, with a peak value in the sepsis group." (PMID 34825737, 2022). "In this study, the combination of ApoC3, VCAM1, B2M, and ApoE proteins were screened and identified as biomarkers for sepsis by using iTRAQ‐2D‐LC‐MS/MS method." (PMID 34825737, 2022). "Median buffy coat TLR-3 mRNA levels were lower in sepsis patients compared with infection, gout and HC groups (0.26 vs 1.67 vs 1.15 vs 1.25 ng/ng B2M, p<0.05)." (PMID 30890150, 2019). "Results of qRT-PCR validated the higher expression level of B2M as well as lower expression level of HLA-DQA1, HLA-DPA1, TAP1, and TAP2 in sepsis samples compared to control samples." (PMID 35685286, 2022). "Results of qRT-PCR validated the higher expression level of B2M as well as lower expression level of HLA-DQA1, HLA-DPA1, TAP1, and TAP2 in sepsis samples compared to control sample." (PMID 35685286, 2022). "Higher TLR-7 levels were found in infection patients than in the gout and HC groups (0.46 vs 0.28 vs 0.30 ng/ng B2M, p<0.05), whereas lower TLR-9 levels were found in sepsis than infection and HC groups (0.015 vs 0.034 vs 0.025 ng/ng B2M, p<0.05)." (PMID 30890150, 2019). "Compared with healthy controls, B2M was significantly upregulated in sepsis samples yet the expression level of HLA-DQA1, HLA-DPA1, TAP1, and TAP2 was significantly lower in sepsis specimens." (PMID 35685286, 2022). "Although we did not measure B2M levels in serum, we observed a significant increase in CSF B2M concentrations in patients with sepsis." (PMID 31063510, 2019).
atherosclerosis (7 papers, 2017 to 2025). A disease characterized by the build-up of fatty material and calcium deposition in the arterial wall resulting in partial or complete occlusion of the arterial lumen. "While, in atherosclerosis, interactions were found between up-DEGs including B2M (combined score: 0.978), CNDP2 (combined score: 0.969) interacted with cysteine." (PMID 38415056, 2024). "Among the 526 upregulated DEGs, were several well‐established genes associated with atherosclerosis plaques, such as matrix Gla protein, VIM, and B2M (Fig EV4D)." (PMID 38031960, 2023). "Furthermore, B2M has been demonstrated to induce smooth muscle cell vitrification, which can subsequently result in atherosclerosis by means of a mediation process involving inflammatory response factors, including soluble viscous molecules." (PMID 40837565, 2025). "Moreover, the STARNET study indicated that CD8+ T cells indirectly communicated with TAP2 through TAPBP and B2M, which suggested that there may be an immune system imbalance in the atherosclerosis process." (PMID 38720469, 2024).
colon adenocarcinoma (7 papers, 2008 to 2024). "For colon adenocarcinoma, the somatic mutations in four genes were significantly enriched in protein pocket regions: B2M (P = 3.1 × 10-4), IFNA2 (P = 3.1 × 10-4), VAV3 (P = 6.6 × 10-4), and ETV6 (P = 1.0 × 10-3)." (PMID 25360158, 2014). "COAD (Colon Adenocarcinoma) is enriched with B2M, PTEN, and RNF43 double mutations." (PMID 36808143, 2023).
colorectal tumors (7 papers, 2010 to 2025). "MSI-h colorectal tumors commonly show biallelic disruption of the B2M gene that affects their MHC class I surface expression and the effectiveness of anti-PD1 therapy." (PMID 36068918, 2023). "COX-2 mRNA levels, normalized with respect to tissue weight or mRNA levels of the housekeeping genes B2M or GAPDH, were over-expressed in 80%, 70% and 40% of the colorectal tumor tissues, as compared to the paired adjacent normal colorectal mucosa samples, respectively." (PMID 24383454, 2014).
coronary heart disease (7 papers, 2021 to 2024). "Further, a proteomic study found plasma B2M to be a risk marker for coronary heart diseases in postmenopausal women." (PMID 33467687, 2021). "Few prospective studies explored the association of beta-2-microglobulin (B2M) with coronary heart disease (CHD) mortality." (PMID 35647083, 2022).
depression (7 papers, 2012 to 2025). "B2M has also been implicated in other neuropsychiatric disorders (alcoholism, autism, depression, eating disorders, pain, as well as aging and suicide), possibly mediating the effects of stress in those disorders." (PMID 30862937, 2020). "In conclusion, our study provides evidence that B2M induces depression-like behaviors in the TST, FST, and NSF tests of rats." (PMID 29795686, 2018). "Our present findings suggest that target B2M might represent a novel approach for treatment of depression and anxiety." (PMID 29795686, 2018). "It has been known that B2M impairs neurogenesis and has related to clinical depression." (PMID 29795686, 2018). "Furthermore, several studies identify that the levels of B2M is increased in the serum or urine of major depressive disorder." (PMID 29795686, 2018). "Regulation of the levels of B2M might reveal a novel therapeutic approach for the treatment of depression and anxiety." (PMID 29795686, 2018). "Out of our 26-analyte panel, only three proteins (ApoH, ApoA1 and B2M) were altered in bipolar disorder patients and four (MIF, ACE, TNC and ILra) were changed in patients with depression." (PMID 26171982, 2015). "b2M and TNF-RII have been previously recognized as depression-specific serum protein biomarkers." (PMID 28594820, 2017). "In addition, B2M also was considered as a housekeeping gene for discriminated asthma with or without depression." (PMID 29795686, 2018). "It is worthy to speculate whether B2M impairs neurogenesis and induces depressive- and anxiety-like behaviors are relate to inhibiting the expression of BDNF and exogenous giving BDNF can reverse the toxicity of B2M in neuroprotective depression and anxiety disease?" (PMID 29795686, 2018). "After analysis and comparison using three different statistical methods, B2M and RPLP0 were identified as the most suitable HKGs for gene expression studies in uncultured CD4+ T cells of asthmatics with or without depression." (PMID 23110234, 2012).
neuroblastoma (7 papers, 2008 to 2023). Neuroblastoma (NB) is the most common solid, extracranial childhood tumor. "Moreover, induced MMR deficiency decreases MHC class I-related and B2M gene expression in neuroblastoma cells, rendering them less sensitive to CD8+ T cell cytotoxicity and potentially anti-PD1 therapy." (PMID 36068918, 2023). "Overall, these data show at the single molecule level that the mobility of GM1 in living neuroblastoma cells is altered by b2M aggregates, further supporting the idea that this lipid is a key interaction site even for the aggregates formed by this protein." (PMID 26990223, 2016). "We observed that HLA class I loss was associated in most cases with low transcriptional levels of HLA class I, TAP1/2 and B2M across several tumor types, by RT-qPCR (Taqman assay) using a panel of PDXs, particularly in neuroblastoma, rhabdomyosarcoma, and nephroblastoma." (PMID 38318504, 2023). "B2M is also an interesting gene specifically for neuroblastoma." (PMID 37046768, 2023). "For example, it has been reported that B2m (beta-2-microglobulin, a commonly used reference gene) is variably expressed in neuroblastoma cells, depending on the differentiation state of the tumour cells, warranting the validation of a reference gene in each experimental system." (PMID 18954449, 2008). "Therefore, we compared B2M gene expression among pMMR and idMMR neuroblastoma cells." (PMID 36068918, 2023). "Notably, HLA-B, TAP1 and TAP2 transcript levels were lower than the minimum values of control normal tissues (brain and testis) in ~80% of PDXs (32 out of 44), and B2M levels were also low in neuroblastoma, nephroblastoma, and all but one rhabdomyosarcoma tumors." (PMID 38318504, 2023). "We therefore applied these criteria to identify potential HK genes for SY5Y cells, also checking the expression of commonly used HK genes for qPCR normalization in neuroblastoma experiments involving cell lines, such as ACTB, B2M, and GAPDH." (PMID 34066513, 2021). "For 34 neuroblastoma samples, the proposed new algorithm yielded the smallest upper bound for the variance of the geometric mean of six genes, ACTB, B2M, GAPDH, HPRT1, TBP, and YWHAZ." (PMID 20470420, 2010). "Our data suggest that this downregulation is not mediated by specific expulsion of B2M mRNA from the neuroblastoma cells." (PMID 37046768, 2023).
pancreatic cancer (7 papers, 2020 to 2025). "Higher expression of B2M was found in pancreatic tissue of patients with chronic pancreatitis (CP) or pancreatic tumors than in normal individuals in the independent cohort (all p < 0.05)." (PMID 38388766, 2024). "In GR-knockdown or mifepristone-treated HY24409 pancreatic tumors, knockdown of B2M depleted surface MHC-I in vivo, decreased the percentages of tumor-infiltrating CD8+ T cells and granzyme B+ CTLs, and rescued tumor growth." (PMID 34873175, 2021). "B2M is known to be involved in T-cell modulation in the pancreatic cancer pathway." (PMID 39161381, 2024). "Relative to the control group, mifepristone-treated pancreatic tumors showed a decrease in cell-surface PD-L1 as well as an increase in cell-surface MHC-I (H-2Kb) and B2M, either with or without co-treatment with dual ICB." (PMID 34873175, 2021).
Arthritis (6 papers, 2019 to 2024). Inflammation of a joint. "The incidence of spontaneous development of arthritis decreased by 33% in HC10-treated animals compared with mAb ME1 (specific for B2m-associated HLA)-treated and PBS-treated animals." (PMID 39057057, 2024). "In a past study, HPRT1, B2M, and RPL13A were the stable genes in the arthritic joints of the KbxN serum transfer arthritis model, and the mRNA expression level of GAPDH significantly decreased with an increase in joint inflammation." (PMID 37894839, 2023). "Spontaneous arthritis was also observed in HLA-B27 transgenic mice lacking B2m (HLA-B27+ B2m−/−) but not in HLA-B27+ B2m+/− mice." (PMID 37627243, 2023). "Spontaneous arthritis occurs in HLA-B27+ mice lacking B2m (HLA-B27+ B2m−/−) but not in HLA-B27+ B2m+/− mice." (PMID 37627243, 2023). "This is critical because HLA-Ia HCs without B2m are well known to be expressed on activated immune cells and other cells activated by cytokines, inflammation, and inflammatory factors such as arthritis." (PMID 38390869, 2024).
gastric cancer (6 papers, 2010 to 2025). A primary or metastatic malignant neoplasm involving the stomach. "Beta 2-microglobulin (B2M) binds to human leukocyte antigen (HLA) class 1, a transmembrane protein, and HLA expression in gastric cancer has been implicated in prognosis." (PMID 37952025, 2023). "In our study, however, 6 out of 25 (24%) tumors presented with biallelic B2M mutations (4 colorectal, 2 gastric cancers), demonstrating that B2M mutations can also occur in stage IV MSI GI cancers." (PMID 34168989, 2021). "miR-340-5p targets beta 2-microglobulin, albeit reportedly involved in the regulation of gastric cancer development and apoptosis." (PMID 37952025, 2023). "For example, the most unstable gene, HPRT1, in 'stomach cancer cell lines' has much wider range of expression compared to GAPDH or B2M." (PMID 20507635, 2010). "The RQ of GPNMB expression by each six single reference genes and B2M-GAPDH combination in 'stomach cancer cell lines' was compared." (PMID 20507635, 2010). "Patterns of RQ in 'stomach cancer cell lines' were similar to RQ by B2M-GAPDH, but RQ of 'all stomach tissues' by 18S rRNA-ACTB were different from." (PMID 20507635, 2010). "The RQs by B2M, GAPDH as single reference gene and B2M-GAPDH that were predicted to be the most optimal combination of reference genes for 'stomach cancer cell lines' by geNorm showed similar high-low patterns." (PMID 20507635, 2010). "Taking these findings together, B2M seems to be the most suitable single reference gene for 'stomach cancer cell lines' and RPL29 for 'all stomach tissues'." (PMID 20507635, 2010). "However, higher expression of ACTB and B2M was reported in stomach tissues than AGS/SNU-638 stomach cancer cell lines as well as higher B2M expression in liver tissues than HepG2/Hep3B/SK-HEP-1/SNU-182 liver cancer cell lines." (PMID 20507635, 2010). "NormFinder also identified B2M as the best reference gene for 'stomach cancer cell lines', RPL29-B2M for 'all stomach tissues', and 18S rRNA-ACTB for 'all stomach cell lines and tissues'." (PMID 20507635, 2010). "This study validated RPL29 and RPL29-B2M as the best single reference genes and combination, for RT-qPCR analysis of 'all stomach tissues', and B2M and B2M-GAPDH as the best single reference gene and combination, for 'stomach cancer cell lines'." (PMID 20507635, 2010). "The stability analyses by geNorm suggest B2M-GAPDH, as best reference gene combination for 'stomach cancer cell lines'; RPL29-HPRT1, for 'all stomach tissues'; and ACTB-18S rRNA, for 'all stomach cell lines and tissues'." (PMID 20507635, 2010). "Thus, we applied non-parametric Mann-Whitney U-test for comparing non-normal distributed unmatched groups, and it showed significant differences in the expressions of GAPDH (p = 0.014) and B2M (p = 0.035) between 'stomach cancer cell lines' and 'non-stomach cancer cell lines'." (PMID 20507635, 2010).
Hypercalcemia (6 papers, 2015 to 2025). An abnormally increased calcium concentration in the blood. "Significant correlations were observed between serum miR-16 expression levels and Cr (r = −0.473, p = 0.002), GFR (r = −0.466, p = 0.001), Cr ≥ 2 (r = −0.562, p = 0.002), hypercalcemia (r = −0.460, p = 0.003), B2M (r = −0.370, p = 0.021), and CRP (r = −0.356, p = 0.022)." (PMID 38892251, 2024).
liver cancer (6 papers, 2008 to 2023). An epithelial or non-epithelial malignant neoplasm that arises from the liver. "Baseline cell surface HLA-I and B2M expression varied between the 5 liver cancer cell lines, Huh7, SNU398, PLC/PRF/5, HepG2, and SNU387." (PMID 34458148, 2021). "In hepatic cancer cell lines, B2M, GAPDH, UBC, and HPRT1 were the first four stable nominees, respectively, and RNA18S was determined as the least stable ones." (PMID 34752497, 2021). "Similarly, a panel of five reference genes, namely ACTB, HPRT1, UBC, YWHAZ, and B2M is also recommended for RT-qPCR data normalization of three hepatic cancer cell lines, including Huh7, HepG2, and PLC-PRF5." (PMID 34752497, 2021). "Besides that, a panel of five nominees, including ACTB, HPRT1, UBC, YWHAZ, and B2M showed higher stability than others in hepatic cancer cell lines." (PMID 34752497, 2021). "In hepatic cancer cell lines, the first six stable reference genes were YWHAZ, ACTB, B2M, UBC, HPRT1, and RNA18S." (PMID 34752497, 2021). "We treated liver cancer cell lines with regorafenib in the presence or absence of IFNγ, and evaluated the cell surface levels of HLA-I and B2M protein by flow cytometry." (PMID 34458148, 2021). "Moreover, in hepatic cancer cell lines including Huh7, HepG2, and PLC-PRF5, ACTB, HPRT1, UBC, B2M, and YWHAZ were among the first six stable genes ranked by geNorm, NormFinder, and RefFinder algorithm." (PMID 34752497, 2021). "Moreover, for the studied cell lines, it is proposed that not to use ACTB and B2M; and TBP for normalizing the breast and hepatic cancer cell lines derived RT-qPCR data, respectively." (PMID 34752497, 2021).
liver disease (6 papers, 2014 to 2025). "We then selected three of the top upregulated or downregulated genes in aging for further studies in liver diseases/cancer: B2M (upregulated with age), C1qA (upregulated with age), and SUCLG1 (downregulated with age)." (PMID 39941711, 2025). "On the contrary, only one out of 19 patients with B2M-wild type tumors had an exclusively peritoneal/peritoneal and lymph node metastatic pattern (p=0.0055), but 10/19 patients showed extensive hepatic disease." (PMID 34168989, 2021). "B2M, CEA, GDF15, IGFBP2, OPN and PDGF-Rb, which are uncertain about the association with liver cancer but have involvement in liver diseases or multiple cancers; 3)." (PMID 30220970, 2018). "The greatest variation was noted for B2M, a putative tumor marker that is also increased in liver disease." (PMID 29211799, 2017). "While B2M and C1qA did not display any change across the spectrum of liver disease, SUCGL1 mRNA expression decreases significantly and progressively with the deterioration of liver disease, reaching the lowest levels in malignant settings, i.e., HCC and CC." (PMID 39941711, 2025). "The other 6 proteins tested were chosen because of their reported involvement in liver diseases (e.g. GDF15, which has been shown to be involved in liver disease and hepatocellular carcinoma) and other cancers (as is the case for CEA, IGFBP2, B2M, PDGF-Rb and OPN)." (PMID 30220970, 2018). "Beta-2 microglobulin is a component of major histocompatibility complex (MHC)/human leukocyte antigen (HLA) class I molecules, and high serum levels are generally present in hematological malignancies and in nonneoplastic renal and liver diseases." (PMID 24692843, 2014).
mastitis (6 papers, 2009 to 2023). Inflammation of breast tissue during lactation or postpartum due to an obstructed duct or infection. "Proteomic 2DE analysis of whey samples from cows and sheep with mastitis including subclinical mastitis have revealed elevated levels of beta-2-microglobulin." (PMID 33260718, 2020). "Two other genes encoding proteins present in milk during lactation or mastitis were found to be associated with segmental duplications: cathelicidin (CATHL1) and β-2 microglobulin (B2M)." (PMID 19951423, 2009). "Interestingly, beta-2-microglobulin was shown to increase by several folds in S. aureus mastitis but decreased significantly in an experimental S. uberis intramammary challenge compared to controls." (PMID 37889706, 2023). "XS up-regulated expression of anti-bacterial genes (LTF and B2M), which may be beneficial to the host by preventing the incidence of mastitis." (PMID 30009039, 2018).